EGFR (epidermal growth factor receptor)
Diseases named in the same sentence as EGFR in open-access papers (continued):
Sharing a sentence is not in itself a finding about the gene and the disease.
lung cancer (continued). "Suppression of HDAC6 activity via honokiol leads to disrupting EGFR and Hsp90 association following by EGFR degradation in lung cancer." (PMID 32180962, 2020). "First‐generation EGFR TKIs, such as Gefitinib and Erlotinib, reversibly bind to EGFRs, thereby improving the survival of patients with lung cancer which harbor EGFR‐activating mutations." (PMID 32395702, 2020). "Based on these results, a large majority of patients with advanced EGFR mutation‐positive lung cancers received osimertinib as the first‐line therapy." (PMID 32495514, 2020). "For example, nonsmall cell lung cancer patients tested positive for plasma EGFR mutation have been approved eligible for EGFR tyrosine kinase inhibitors." (PMID 33377634, 2020). "At present, EGFR‐TKI is widely used in the treatment of EGFR‐sensitive mutation lung cancer patients, and significantly improves the prognosis of patients." (PMID 32395869, 2020). "For example, an anti-EGFR (epidermal growth factor receptor) antibody had a dramatic response on lung cancer with EGFR mutations." (PMID 33299012, 2020). "In lung cancer patients, EGFR mutations are readily detectable in liquid biopsies as an alternative to tissue biopsy." (PMID 32650387, 2020). "The p.Thr790Met point mutation (T790M) in the gene encoding EGFR is the most common cause of TKI resistance in lung cancer; it can reduce binding of TKIs to EGFR." (PMID 32298306, 2020). "The discovery that sensitizing epidermal growth factor receptor (EGFR) mutations are predictive for therapeutic benefit from EGFR tyrosine kinase inhibitors (TKIs) such as erlotinib marked the beginning of a new era in lung cancer therapeutics." (PMID 32313757, 2020). "Identification of EGFR mutations is critical to the treatment of primary lung cancer and brain metastases (BMs)." (PMID 32483122, 2020). "EGFR tyrosine kinase inhibitors (TKIs) have shown successful clinical outcomes in various solid cancers harboring EGFR mutations, especially lung cancer." (PMID 33142709, 2020). "Next, EGFR mutations were associated between lung cancer tissues and the NM CSF samples available in 10 patients." (PMID 32711494, 2020). "In total, 29.3% of lung cancer patients harbored an epidermal growth factor receptor (EGFR) exon 19 deletion or an exon 21 L858R mutation." (PMID 33014793, 2020). "This is the first reported case involving EGFR exon 21 p.L858R, a gene mutation associated with non‐small cell lung cancer (NSCLC), in a BA." (PMID 33063939, 2020). "The authors reported that silencing DGKη in lung cancer models, characterized by EGFR and KRAS mutations, reduced cancer cell growth while enhancing the cells’ sensitivity to EGFR inhibitor Afatinib." (PMID 32722576, 2020). "Alterations in EGFR in the form of overexpression, amplification, or mutations are postulated to contribute to the development or propagation of lung cancer by enhancing cellular proliferation, apoptosis inhibition, and angiogenesis." (PMID 33247670, 2020). "Several reports revealed that afatinib, an irreversible pan‐ErbB family blocker, has potential activity against osimertinib‐resistant lung cancer because it has been proven effective against tumors with both minor and compound EGFR mutations." (PMID 32495514, 2020). "The first‐line standard treatment of non‐small cell lung cancer (NSCLC) with EGFR mutation is EGFR‐tyrosine kinase inhibitors (TKIs)." (PMID 32163227, 2020). "Recent studies uncovered that lung cancers with classical EGFR mutations, such as exon 19 and exon 21 L858R mutation, are a heterogeneous disease in terms of response to EGFR-TKI treatment." (PMID 32929081, 2020). "This indicated that MALAT1 can serve not only as a diagnostic marker for EGFR‐mutant lung cancer, but also as an important potential marker for monitoring the efficacy of EGFR‐TKI therapy." (PMID 31691525, 2020).
lung cancer (continued). "Fibrinogen is a valuable biomarker to predict tumor status, EGFR mutation status, and clinical outcome in patients with lung cancer and is associated with tumor progression and metastasis." (PMID 33817221, 2020). "Currently, lung cancers are screened for actionable mutations, to identify cases suitable for targeted therapies, including those targeting mutations in EGFR, BRAF and rearrangements in ALK or ROS1." (PMID 32898185, 2020). "In our study, most of the kinase β3‐αC loop alterations found in lung cancer were from EGFR with all β3‐αC indels, and 34% of point mutations in this region were drug‐relevant alterations." (PMID 32757330, 2020). "Osimertinib has a special role to play in clinics against lung cancers, particularly with mutated EGFR that confers resistance." (PMID 32641854, 2020). "Histologically diagnosed types of primary lung cancer included adenocarcinoma (27/32, 84.3% for EGFR wild type vs. 28/29, 96.6% for EGFR mutation) and small cell (5/32, 15.7% for EGFR wild type vs. 1/29, 3.4% for EGFR mutation, p = 0.26)." (PMID 32483122, 2020). "We analyzed the potential value of these features for predicting EGFR mutation status in primary lung cancer cases." (PMID 32483122, 2020). "Given that EGFR-mutated lung cancers are known to be resistant to anti-PD1 therapies, these findings support a deleterious effect of sPD-L1 expression on nivolumab efficacy in NSCLC patients." (PMID 32085544, 2020). "Non-small cell lung cancer (NSCLC) accounts for 80% of all lung cancer cases, with mutation of the epidermal growth factor receptor (EGFR) found in 10–15% in Caucasian patients." (PMID 33272243, 2020). "Mutations in the EGFR gene have been discovered to be strongly associated with lung cancers, especially LUAD." (PMID 32210009, 2020). "ASK120067 caused EGFR T790M tumor shrinkage in a lung cancer patient with acquired resistance to early-generation EGFR TKIs in a clinical trial." (PMID 32404161, 2020). "We previously reported that the susceptibility of EGFR- mutated lung cancer cells to EGFR-TKIs including osimertinib inversely correlated with the expression of AXL in tumor cells." (PMID 32929081, 2020). "In a report, the International Association for the Study of Lung Cancer recommended the use of LB techniques to detect EGFR mutations in treatment naïve patients." (PMID 32365836, 2020). "Bevacizumab, a recombinant monoclonal antibody targeting VEGF‐A, is one of the most widely available anti‐VEGF therapies and has demonstrated a synergistic effect with EGFR‐TKIs against EGFR mutation‐positive lung cancers." (PMID 32495514, 2020). "EGFR mutations have been well-characterized in lung cancer due to their relationship to clinical responses to EGFR tyrosine kinase inhibitors." (PMID 31940362, 2020). "Long-term smoking is well-known to be the main cause of lung cancer, while environmental effects (e.g., air pollution and particulate matters) and genetic variations (e.g., KRAS and EGFR mutations) can also cause lung cancer." (PMID 33233641, 2020). "Lung cancers with EGFR mutations are often “driven” by EGFR activation and are sensitive to erlotinib, resulting in a prolonged lifespan for these lung cancer patients." (PMID 32929368, 2020). "Generally, EGFR mutations such as L858R expression and Exon 19 in-frame deletion indicate favorable treatment outcomes compared with individuals with lung cancer and wild-type EGFR in terms of relapse-free and overall survival." (PMID 33050100, 2020). "The outcome of patients with EGFR mutated lung cancer with bone metastases have been evaluated in six published papers in which the SRE frequency was 0% in only one paper, while ranged between 20 and 51% in the remaining five papers." (PMID 33282740, 2020). "TRIM27 is associated with poor prognosis of lung cancer with EGFR mutations, and it has been reported to regulate migration, invasion, and proliferation of lung cancer cells." (PMID 33264103, 2020).
lung cancer (continued). "In agreement with our finding, more ground-glass opacity and less solid components were observed in lung cancers with EGFR mutation with lower mean CT values when compared to those with wild-type EGFR." (PMID 33134170, 2020). "Here, we present a patient with multiple EGFR mutations that highlights tumor heterogeneity leading to a mixed molecular response to targeted drugs and emphasizes the complexity of EGFR‐driven lung cancer." (PMID 32776462, 2020). "In recent years, there have been a number of published research reports about the effect of driver gene mutations on brain metastasis in lung cancer patients, among which EGFR is the most concerning factor." (PMID 31769228, 2020). "It has been demonstrated that activation of EGFR mutation is associated with enhanced PD-L1 expression in human lung cancer cells which is reduced by EGFR inhibitors." (PMID 33287803, 2020). "The clinical relevance of our results lies in the development of a novel imaging biomarker for BM EGFR mutation status in lung cancer patients." (PMID 32483122, 2020). "At present, few studies based on PET/CT radiomics have predicted the survival of lung cancer patients with EGFR mutations, and their predictive performances were generally poor." (PMID 33262942, 2020). "Lung cancer driver genes mainly include EGFR, ERBB2, MET, RET, ALK, and ROS1, all encoding genes for receptor tyrosine kinases (RTKs)." (PMID 33537237, 2020). "EGFR is one of the most commonly mutated genes in lung cancer patients, especially in Asia where an incidence of 40–60% was observed." (PMID 32412152, 2020). "In lung cancers, CD44v9 expression correlates significantly with early-stage lung adenocarcinoma and epidermal growth factor receptor (EGFR) mutations." (PMID 32849491, 2020). "Epidermal growth factor receptor (EGFR) tyrosine kinase inhibitors (TKIs) provide clinical benefits over chemotherapy for lung cancer patients with EGFR activating mutations." (PMID 32123859, 2020). "In this study conducted using plasma samples collected from 185 NSCLC patients, Sel-Cap, a digital enrichment NGS-based lung cancer panel, shows very high sensitivity for EGFR mutations in cfDNA, even in early-stage disease." (PMID 33266057, 2020). "In 2019, Creelan and colleagues conducted a Phase I clinical trial testing the combination of dasatinib and afatinib on 25 lung cancer patients with activating mutations on EGFR exon 19 or 21 or disease progression following prior EGFR-TKI therapy." (PMID 32517369, 2020). "Genetic mutation of epidermal growth factor receptor (EGFR) gene is one of the critical therapeutic markers for lung cancer." (PMID 33007940, 2020). "In non‐small cell lung cancer, sensitizing mutations in epidermal growth factor receptor (EGFR) or cMET amplification serve as good biomarkers for targeted therapies against EGFR or cMET, respectively." (PMID 31960422, 2020). "Since 2016, approximately 16,000 EGFR mutations in lung cancer had been registered in the COSMIC (the catalog of somatic mutations in cancer) database." (PMID 32833992, 2020). "Somatic EGFR mutations were frequent in lung cancers, whereas somatic KRAS and APC mutations were frequent in colorectal cancers." (PMID 33193564, 2020). "Of these mutations, 97.8% (1583/1616) were found in lung cancer, with 96.71% (1530/1583) of the mutations in lung cancer were located in EGFR, 1.1% (17/1583) located in ERBB2, 0.7% (12/1583) located in BRAF, and 1.4% (23/1583) in MAP2K1." (PMID 32757330, 2020). "In view of these findings in lung cancer in Asians, our findings regarding EGFR expression and mutations will provide further options for potential treatment of OSSN for pre- and post-surgical treatment." (PMID 32833992, 2020).
lung cancer (continued). "A subset of patients tested for EGFR mutations were evaluated with NGS tests that include other cancer mutation hotspots, enabling assessment of other oncogenes from the EGFR pathway that are frequently mutated in lung cancer." (PMID 32714871, 2020). "Approximately 80% of lung cancers is associated with NSCLC driven by molecular EGFR mutations and ALK receptor tyrosine kinase translocations." (PMID 32913247, 2020). "Here, we present the case of a patient with multiple EGFR mutations that highlights tumor heterogeneity leading to a mixed response to molecular‐targeted drugs and emphasizes the complexity of EGFR‐driven lung cancer." (PMID 32776462, 2020). "In particular, the overexpression of EGFR found in many lung carcinomas is one of the leading causes of poor prognosis." (PMID 32121107, 2020). "EGFR mutations were described in several forms of cancers, such as breast or lung cancers and it is overexpressed in numerous tumors." (PMID 32766254, 2020). "In the current study, we demonstrated that parthenolide treatment decreases the expression of p-EGFR and its downstream molecule AKT and ERK in EGFR mutated lung cancer." (PMID 33292235, 2020). "On the other hand, the EGFR and its mutations influence the progression and managements in various malignancies including the lung carcinoma." (PMID 32365566, 2020). "More recent observations suggest that metabolic remodeling toward glycolysis favors resistance to EGFR inhibitors in EGFR‐mutated lung carcinoma." (PMID 33025742, 2020). "In the past decades, several subtypes of lung carcinoma harboring specific mutations (most notably EGFR, KRAS, and ALK mutations) have been identified, allowing for the development of therapies specifically targeting the mutated pathway." (PMID 31901171, 2020). "In lung cancer, epidermal growth factor receptor (EGFR) tyrosine kinase inhibitor sensitizing mutations co-existing with rare minor EGFR mutations are known as compound mutations." (PMID 30808329, 2019). "Treatment with epidermal growth factor receptor (EGFR)‐tyrosine kinase inhibitors (TKIs) leads to initial response in most patients with EGFR‐mutated non‐small cell lung cancer (NSCLC)." (PMID 30790471, 2019). "EGFR mutation was confirmed to play significant role in modifying tumor microenvironment in lung cancer." (PMID 31801484, 2019). "Among them, germline EGFR mutation carriers affected with lung cancers are more frequently the White ethnicity." (PMID 31703574, 2019). "In lung cancer, AM exhibited a greater genetic heterogeneity of EGFR mutation and ALK rearrangement." (PMID 31703713, 2019). "In contrast to normal epithelial cells, EGF stimulation of lung cancer cell lines that lack DUOX1 promotes EGF-induced EGFR internalization and nuclear localization, associated with induction of EGFR-regulated genes and related tumorigenic outcomes." (PMID 30890751, 2019). "The blood sample collected from a lung cancer patient at baseline as well as at the 9th week of gefitinib treatment (targeting mutated EGFR), produced loose clusters, however, we observed tight clusters on the 12th week of the therapy." (PMID 31138856, 2019). "Our pilot study interrogated the presence of LOH at certain lung-cancer-associated MS markers in cfDNA from NSCLC patients bearing either EGFR- or KRAS-mutated tumors." (PMID 31861832, 2019). "Using the EGFR mutation status established from the lung cancer tissue as the standard, the overall sensitivity, specificity, and positive predictive value (PPV) of the ARMS method were 49.1%, 90%, and 93.3%, respectively." (PMID 31185703, 2019). "Our findings demonstrated a pivotal role for AXL in the intrinsic resistance of EGFR-mutated lung cancer to osimertinib and the emergence of osimertinib-tolerant cells." (PMID 30651547, 2019). "To date, observational studies reported conflicting relationships, either positive or neutral, between family history and the presence of EGFR mutation in lung cancer patients." (PMID 31703574, 2019).
lung cancer (continued). "Recently, molecular-based personalized therapy has highly developed in lung cancer field, and tyrosine kinase inhibitor is more effective than chemotherapy for patient with EGFR mutations." (PMID 31448233, 2019). "In lung cancer cancers, epidermal growth factor receptor (EGFR) mutation or anaplastic lymphoma kinase (ALK) fusion transcript status should be considered in conjunction with their intrinsic EMT process." (PMID 31341890, 2019). "A meta-analysis of 16 trials on EGFR TKI treatment in lung cancer patients revealed that pneumonitis was the most common cause of death related to EGFR TKI toxicity." (PMID 31426531, 2019). "The development of PEM resistance in lung cancer with an ALK rearrangement is associated with the activation of the EGFR-HER family, which provides a rationale for the use of the pan-her inhibitor, afatinib, to overcome PEM-acquired resistance." (PMID 31795298, 2019). "Exosomal miR-221 and miR-222 presence was linked to a good response to osimertinib in EGFR-mutated lung cancer patients." (PMID 31242686, 2019). "We showed the effect of afatinib, tyrosine kinase inhibitor for lung cancer with EGFR gene mutation, on PC‐9 cells similarly increased through suppressing the MF characteristics of MRC‐5 by SK‐216." (PMID 30734495, 2019). "EGFR-tyrosine kinase inhibitors (TKIs) have recently been developed as therapeutic agents for patients with lung cancer carrying EGFR-activating mutations." (PMID 30609749, 2019). "AXL was highly expressed in clinical specimens of EGFR-mutated lung cancers and its high expression was associated with a low response rate to EGFR-TKI." (PMID 30651547, 2019). "Currently, there is a phase I study of SAHA combined with gefitinib in patients with BIM polymorphysim associated resistant EGFR mutant lung cancer (ClinicalTrial.gov identifier: NCT02151721)." (PMID 31261881, 2019). "Randomized phase III trials have established the efficacy of epidermal growth factor receptor (EGFR) tyrosine kinase inhibitors as first-line treatment for EGFR mutation-positive advanced non–small-cell lung cancer (EGFR Mut+ NSCLC)." (PMID 30608948, 2019). "These mutations confer sensitivity to EGFR tyrosine kinase inhibitors (TKIs) such as erlotinib, gefitinib and afatinib, current standard of care therapies for the treatment of this subset of lung cancer." (PMID 31291990, 2019). "As the most reported germline mutation, T790 M accounted for 1.0% (5/503) in EGFR-mutated lung cancers from the US." (PMID 31703574, 2019). "EGFR mutations have a good response to EGFR-tyrosine kinase inhibitors (TKIs), which are widely prescribed to treat lung cancer." (PMID 31426797, 2019). "In lung cancer patients, mutations in the EGFR tyrosine kinase (TK) domain are associated with lung tumorigenesis and increased sensitivity to drugs that inhibit EGFR kinase activity." (PMID 30790152, 2019). "Mutations on the epidermal growth factor receptor (EGFR) genes are known to alter sensitivity of treatment in lung cancer." (PMID 31442277, 2019). "Nevertheless, though diverse EGFR mutations are present, the overall survival of lung cancer patients is markedly improved with TKI therapy." (PMID 31058077, 2019). "We performed amplicon-based targeted sequencing with the molecular barcoding system (MBS) to detect major common EGFR mutations and uncommon minor mutations at a 0.5% allele frequency in fresh–frozen lung cancer samples." (PMID 30808329, 2019). "Patients with epidermal growth factor receptor (EGFR) mutation-positive lung cancer show a dramatic response to EGFR-tyrosine kinase inhibitors (TKIs)." (PMID 30609749, 2019). "Lung cancer patients with EGFR mutations had significantly lower TMB values than those with wild‐type EGFR, and increased TMB was significantly associated with dMMR in colorectal cancer (CRC)." (PMID 31270941, 2019).